MGP (matrix Gla protein)
Diseases named in the same sentence as MGP in open-access papers (continued):
Sharing a sentence is not in itself a finding about the gene and the disease.
tumor (continued). "On the one hand, there is a negative correlation of MGP expression with tumor progression and metastasis in renal and prostate carcinoma." (PMID 30257426, 2018). "The role of MGP produced by cancer cells remains still not clear and its main function seems to be limited mainly to tumor environment." (PMID 30257426, 2018). "Special attention should be given to the suggested therapeutic effect of vitamin K on cancer progression and to the potential detrimental effects of vitamin K antagonists widely used in therapy of patients with cancer, on the functionality of VKDPs present in tumor tissues such as GRP and MGP." (PMID 24949434, 2014). "Interestingly, the same heterogeneous pattern was found for MGP, GGCX, and VKOR, while OPN and TNFα were found clearly upregulated in tumor samples." (PMID 24949434, 2014). "The tumorigenesis of SPN may be closely related to oxygen metabolism, MYC targets, and DNA repair;SPN tumor cells may originate from pancreatic endocrine progenitor cells;NOV, DCN were nominated as primary and S100A10, MGP as recurrent SPN marker genes, respectively." (PMID 40312910, 2025). "While providing new mechanistic insights into the pathogenic function of OCSC, our findings pave the way to further investigation on MGP and its downstream effectors in this context, which, in turn, may help designing innovative therapeutic strategies to defeat OCSC-driven tumor progression." (PMID 36977707, 2023). "At the same time, the modulation of so many pathways that are known to play pivotal roles in tumor progression (e.g., hypoxia, angiogenesis, STAT5, etc.) raise the hypothesis that the role of MGP in OC extends well beyond stemness and orchestrates various aspects of cancer development." (PMID 36977707, 2023). "Based on TCGA-LUAD transcriptome data, differential expression analysis showed that with the comparison of normal samples, DKK1 and LOXL2 expression were significantly increased in tumor tissues, whereas MGP and SLIT3 were markedly overexpressed in non-tumoral tissues." (PMID 36185284, 2022). "Even though the aberrant expression of MGP has been associated with disease progression and poor prognosis in a variety of neoplasms, to date, there are no reports on the presence, level of expression and potential roles of MGP in pathological conditions in the oral cavity." (PMID 34205668, 2021). "Some genetic testing methods may be feasible for determining whether tumor tissues highly express RUNX1 and the corresponding downstream genes (BCL3, MGP, and MXI1), consistent with our experimentally validated results: in positive cases, targeting RUNX1 may be a suitable optional treatment." (PMID 31754093, 2019). "Therefore, the role of MGP in tumor progression should be considered from the stromal point of view where MGP–ECM interactions could trigger changes and rearrangements of tumor microenvironment." (PMID 30257426, 2018). "MGP mRNA expression did not correlate with age, gender and location of the tumor." (PMID 19712474, 2009). "This study highlighted the significance of MGP in promoting CRC liver metastasis in the tumor microenvironment, in contrast with the existing studies that were limited to cancer cells only and could not effectively demonstrate the function of MGP in cancer tissues." (PMID 35414780, 2022). "However, higher levels of GRP-F1, MGP, GGCX, and VKOR were found in BC samples that include microcalcifications, suggesting an upregulation associated with calcification, but not necessarily with tumor development." (PMID 24949434, 2014). "Interestingly, genes such as TFF3, MGP, and IGKC were identified across all BL responder tumor cells, irrespective of metastatic site or tissue-specific signatures." (PMID 39955556, 2025). "A dramatic reduction in tumor initiation was observed upon ablation of MGP: at 100 days post-injection, 10 out of 10 mice with OVCAR3-CTR cells developed tumors, while no tumors were observed in the MGP-knockout group." (PMID 36977707, 2023).
tumor (continued). "As for the HNSCC cell lines UM-SCC19 and UM-SCC47, they showed the opposite effect by downregulating the expression of CLEC3B and CCRL1 in the PFs (*** p < 0.001) after tumor cell-fibroblast co-culturing while not affecting the RF marker expression of TGM2 and MGP in the RFs." (PMID 36232952, 2022).
cancer (37 papers, 2014 to 2025). A tumor composed of atypical neoplastic, often pleomorphic cells that invade other tissues. "Although the literature is mostly focused on the role of MGP in calcification and vascular morphogenesis, it has also been associated with the outcome of various cancers." (PMID 41249124, 2025). "Upregulation of MGP promoted cancer proliferation, migration and invasion, that was linked with unfavorable prognosis." (PMID 36185284, 2022). "We suggested that this phenomenon was associated with the complicated secretory mechanism of MGP in cancer cells." (PMID 32405535, 2020). "Several reports have described an association of VKDPs with different types of cancer, namely, matrix Gla protein (MGP) and uncarboxylated prothrombin (des-γ-carboxy prothrombin, DCP)." (PMID 24949434, 2014). "TGF-β was commonly expressed by multiple cell types, including cancer cells, stromal cells and BECs, and its expression was upregulated in metastatic LNs, potentially driving the expression of MGP, FN1, SOX4, PDPN, and HEY1 in LECs." (PMID 41249124, 2025). "MGP was constantly upregulated both in the lymphatics of patients with cancer and in vitro LEC cultures." (PMID 41249124, 2025). "Because MGP expression in HLECs was upregulated by cancer conditioning in both the patients’ scRNA-seq data as well as in our in vitro assays, we wanted to determine the functions of MGP on HLECs." (PMID 41249124, 2025). "In this context, we analyzed the function of MGP, which was highly upregulated both in lymphatics in vivo and HLECs in vitro and were able to discover its adhesive function supporting cancer cell binding to LECs." (PMID 41249124, 2025). "Prior studies have demonstrated that ANXA1 and MGP are up‐regulated in various cancers and facilitate cancer immune evasion." (PMID 41176774, 2025). "The results showed a significant increase in Matrix Gla Protein (MGP) in clusters of cancer cells in CRLM." (PMID 38755133, 2024). "Since MGP is dysregulated in several types of cancers, in our analysis, we selected transcription factors known from the literature to be involved in carcinogenesis processes." (PMID 39684309, 2024). "We also provide evidence for a possible role of YY1, GATA1, and C/EBPα in MGP transcription regulation in human cancers." (PMID 39684309, 2024). "The peritoneal TME-dependent induction of MGP expression in OC cells implicates the TME in the regulation of cancer stemness." (PMID 36977707, 2023). "Yet, the biological mechanisms that regulate the functional contribution of MGP to cancer progression remain elusive." (PMID 36977707, 2023). "Co-expression network showed genes closely associated with RAC1 were calculated among which cancer genes such as MUC1, MUC20, CEACAM5, andCCL20 were positively correlated to expression of RAC1 whereas TIMP3 and MGP was negatively correlated." (PMID 37202394, 2023). "As for TGFBI, CFD, and MGP, MM patients displayed the highest median plasma concentration in comparison to the other cancer patients." (PMID 37835457, 2023). "Based on these findings, it is conceivable that the functional contribution of MGP to cancer stemness is not limited to OC." (PMID 36977707, 2023). "In primary cultures from four independent patients, a remarkable upregulation of MGP was observed in cancer cells co-cultured with the TME as compared with cells that had no contact with the TME." (PMID 36977707, 2023). "Elevated in CRC cancer cells, Matrix Gla protein (MGP) increases intracellular free Ca2+ levels, promotes NF-κB phosphorylation, and activates PD-L1 expression, leading to CD8+ TEX." (PMID 37180158, 2023). "Our study employed the latest technique of single-cell RNA sequencing to further verify MGP expression in CRC cancer cell clusters at the single-cell level, thereby making our conclusion more credible." (PMID 35414780, 2022). "The bar chart shows that MGP was relatively highly expressed in the total sample analysis of the cancer cell population." (PMID 35414780, 2022).
cancer (continued). "We observed that simultaneous knockdown of PD-L1 and MGP significantly inhibited the proliferation and invasion of cancer cells and promoted the apoptosis of cancer cells, compared with the unilateral knockdown of PD-L1." (PMID 35414780, 2022). "The results revealed that MGP was significantly upregulated in cancer cell clusters from the primary CRC or liver metastases, compared with that in the corresponding paracancerous tissues via single-cell RNA sequencing." (PMID 35414780, 2022). "Matrix Gla protein (MGP) was originally reported as a physiological suppressor of ectopia calcification and has also been reported to be associated with cancer." (PMID 35414780, 2022). "Matrix Gla protein (MGP) has been widely reported as an extracellular matrix protein with abnormal expression in various types of cancer." (PMID 32086862, 2020). "The analysis and interpretation of immunohistochemical stainings must be done with a great caution since the MGP expression level of individual cancer cells can vary even within a single cancer cell nest." (PMID 30257426, 2018). "To verify MGP expression on protein levels in real cancer patients, we performed immunohistochemistry using paraffin sections." (PMID 30257426, 2018). "Recently, it was proved that MGP binds fibronectin and augments cell adhesion and spreading of cancer cells." (PMID 30257426, 2018). "It has already been proven that MGP binds to fibronectin and vitronectin and augments cell adhesion and spreading of cancer cells." (PMID 30257426, 2018). "The ability of MGP to alter cell interactions with fibronectin is a potential reason for cancer cells and certain embryonic cells to overexpress MGP." (PMID 25210519, 2014). "It is possible that MGP is a multifunctional protein that can act to modify cell-matrix interactions during embryonic life or in cancer cells and also as a calcification inhibitor in selected adult tissues." (PMID 25210519, 2014). "However, the role of MGP in terms of cancer appears complicated, as not only can its expression be considered both beneficial and detrimental, depending on the cancer type, but also its molecular effect seems to vary." (PMID 41249124, 2025). "Among the identified prognostic genes, TIMP1, CXCL8, and MGP have been reported in various cancers." (PMID 40299331, 2025). "To assess whether MGP can mediate cancer cell adhesion, we examined the binding of recombinant MGP to T47D cancer cells in vitro and found that soluble MGP bound significantly to these cells." (PMID 41249124, 2025). "In addition, cancer cell adhesion was decreased in MGP-inhibited LECs and recombinant MGP-bound cancer cells." (PMID 41249124, 2025). "Upregulated MGP promotes cancer cell adhesion to LN lymphatics." (PMID 41249124, 2025). "The impact of MGP on LEC functions was also observed in our cancer cell adhesion experiments." (PMID 41249124, 2025). "VEGF-A is highly expressed in macrophages and in cancer cells, and may induce MGP and atypical chemokine receptor ACKR3, which is a receptor of CXCL12." (PMID 41249124, 2025). "These efforts may help to further determine the clinical significance of MGP across different types of cancer." (PMID 39684309, 2024). "Our discovery of novel transcriptional repressors of MGP may provide new insights into its altered expression in a significant subset of cancers." (PMID 39684309, 2024). "However, the data in TCGA suggested that the GATA1 expression was positively correlated with the MGP expression in cancer tissues." (PMID 39684309, 2024). "In addition, MGP expression is negatively or positively correlated with the studied TFs’ expression levels in several cancer types." (PMID 39684309, 2024). "Our study results add new insights into the metastatic function of MGP in cancer." (PMID 35414780, 2022). "MGP, an extracellular matrix protein, whose well-defined function is still unknown, and currently acts as a double-edged sword in cancers." (PMID 36185284, 2022).
cancer (continued). "According to the dot plot, compared with samples from different parts of the body, MGP was significantly upregulated in cancer cell clusters from the primary CRC tissues; moreover, compared with paracancerous tissues, it was highly expressed in metastatic foci of CRC." (PMID 35414780, 2022). "Matrix Gla protein (MGP), an extracellular matrix protein, is mainly associated with the inhibition of calcification in skeleton, coronary artery, and kidney, and more recently it has also been implicated in cancer." (PMID 32405535, 2020). "Since the interaction of cells with fibronectin lead to increased resistance to different cytotoxic drugs (CAM-DR) and MGP augments this interaction, we have formulated a hypothesis that MGP–fibronectin interaction can intensify CAM-DR in cancer cells." (PMID 30257426, 2018). "The purpose of this analysis was to verify whether the expression of the analyzed MGP gene and protein that was observed in cell lines could also be confirmed in real cancer patient tissues." (PMID 30257426, 2018). "MGP mRNA level (real time PCR analysis) and protein expression in cell lysates and cell culture medium (Western blot analysis) and protein expression in cancer cells (immunofluorescence analysis) and cancer patient lesions (immunohistochemistry) were determined in this study." (PMID 30257426, 2018). "In contrast, MGP was found exclusively in the cytoplasm in the carcinoma cells." (PMID 27556859, 2016). "However MGP is synthesized in many tissues and is especially enriched in embryonic tissues and in cancer cells." (PMID 25210519, 2014). "Hence, these data indicate that YY1 may serve as a negative regulator of MGP and that it may play oncogenic roles in different cancers." (PMID 39684309, 2024). "In addition, the same study proved that MGP might contribute to increased cancer resistance to chemotherapeutic drugs by augmenting the interaction of stromal cancerous cells with the extracellular matrix components." (PMID 35053080, 2022). "Together with our finding in niche model that MGP may constitute a specific malignant microenvironment concomitant with the induction of BMP-4 in mesenchymal cells, MGP might be regarded more broadly as a niche factor that modifies microenvironments to suit cancer stem cells for survival and growth." (PMID 32322728, 2020). "Since it was already proved that MGP may incorporate into fibronectin multimers, e it is also possible that this small molecule may place between collagen fibers and in this way limit drug delivery to the cancer cells." (PMID 30257426, 2018). "Other studies could determine the effect of MGP for migration and invasion assays in HeLa compared to other cancer cell types, but longer term studies need to consider the ability of cells to synthesize fibronectin, MGP, integrins, or metalloproteinases that affect migration and invasion." (PMID 25210519, 2014). "This study showed that MGP is underexpressed in LUAD compared to normal lung tissues; underexpression was correlated with a poorer cancer prognosis." (PMID 40563443, 2025). "MGP silencing and inhibition in LECs increased LEC migration and reduced cancer cell adhesion, respectively." (PMID 41249124, 2025). "When exploring the potential factors enhancing MGP expression, we first chose candidates among the reported factors secreted by cancer cell lines and found that VEGF-A, VEGF-C, and TGF-β upregulate MGP expression in LECs." (PMID 41249124, 2025). "Given the role of CAFs in interacting with cancer cells via growth factors, inflammatory ligands, and ECM proteins,we investigated the correlation between MGP, COL8A2, and PAPPA with CAF markers." (PMID 37777759, 2023). "Matrix Gla protein (MGP) has been connected to the inhibition of calcification and there is evidence of its relation to the progression of different cancers." (PMID 37835457, 2023).
cancer (continued). "To further prove the significance of MGP expression in PAC and TOP resistance, we performed experiments with short time exposure of cancer cells to investigated drugs." (PMID 30257426, 2018). "The first one presumes that MGP molecules, found both intracellularly and extracellularly, can bind PAC and TOP molecules limiting their availability for cancer cells." (PMID 30257426, 2018). "Although at present no MGP- or RUNX2-specific inhibitors have been approved for cancer treatment, these molecules are under active investigation as potential therapeutic targets." (PMID 39684309, 2024). "In particular, no information is available on the role of MGP in cancer stem cells (CSC), and also its involvement in OC development has not been investigated." (PMID 36977707, 2023). "The expression of MGP has been investigated in several cancer types, but no clear role has been established." (PMID 29303985, 2018). "Although increasing sample sets, not yet available in our laboratory, would be required to clearly establish a relation between GRP-F1 expression levels and cancer development, it is interesting to note that expression pattern of GGCX, VKOR, and MGP was found highly similar to that of GRP-F1." (PMID 24949434, 2014). "Furthermore, we tested the role of MGP on cancer cell adhesion to LN lymphatics using metastatic and non-metastatic lymph node sections of four patients and T47D cells in ex vivo adhesion assays." (PMID 41249124, 2025). "Since MGP has never been associated with OCSC and very little is known about its function in cancer, we decided to investigate whether it plays any role in OCSC pathophysiology." (PMID 36977707, 2023). "In agreement with the possible involvement of MGP in various cancer-related processes not necessarily related to OCSC, we observed a widespread distribution of the protein (i.e., not restricted to small cancer cell subpopulations) in various OC specimens within our tissue microarrays." (PMID 36977707, 2023).